EGFR (epidermal growth factor receptor)
Diseases named in the same sentence as EGFR in open-access papers (continued):
Sharing a sentence is not in itself a finding about the gene and the disease.
colorectal cancer (continued). "The anti-EGFR therapies have shown to be effective only in a subset of patients with colorectal cancer." (PMID 25267307, 2014). "This notion stems from the fact that, in colorectal cancer, mutations of KRAS/BRAF genes, which are integral part of the EGFR signaling pathway make EGFR inhibitors ineffective." (PMID 28326248, 2014). "In BRAFV600E mutant colorectal cancer cells, which generally express higher levels of EGFR than melanomas, activation of EGFR and downstream pathways occurs in response to vemurafenib and is responsible for resistance towards this BRAF inhibitor." (PMID 24970815, 2014). "In colorectal cancers, KRAS mutations are known to determine the clinical efficacy and acquired resistance to EGFR targeting." (PMID 24970817, 2014). "Oncogenic mutational analysis provides predictive guidance for therapeutics such as anti-EGFR antibodies, but it is successful only for a subset of colorectal cancer (CRC) patients." (PMID 25090459, 2014). "PI3K can serve as an effector of activated K-Ras in pancreatic cancer cells and K-Ras activity can modulate EGFR activation in colorectal cancer cells." (PMID 25180228, 2014). "Immunohistochemical staining for mTOR, EGFR and PTEN was motivated by these markers being key targets that have also been shown to be up-regulated in Lynch syndrome-associated colorectal cancer." (PMID 24848881, 2014). "Comparable to the situation in HER2-amplified breast cancer, substantial progress has been made by the introduction of EGFR-targeted therapies in the treatment of lung cancer and colorectal cancer." (PMID 24879454, 2014). "For instance, KRASG12V confers greater resistance to EGFR inhibitors in colorectal cancer, while KRASG13D is associated with worse overall survival of colorectal cancer patients treated with standard chemotherapy." (PMID 24465899, 2014). "KRAS mutations in codons 12 and 13 are established predictive biomarkers for anti-EGFR therapy in colorectal cancer." (PMID 24885062, 2014). "For example, a recent paper examining colorectal cancer cells grown in 3D, observed a similar phenomenon, where all seven cell lines studies had lower EGFR protein expression compared to 2D monolayer cells." (PMID 24638075, 2014). "The development of targeted therapies, including anti-EGFR monoclonal antibodies (such as panitumumab and cetuximab), has been beneficial to colorectal cancer patients, and these therapies are becoming standards for treatment of metastatic colorectal cancer." (PMID 25427200, 2014). "Our previous study has shown that ARNO is the most important cytohesin and is over expressed in colorectal cancer cell lines as an activator that plays a crucial role in EGFR pathway signaling." (PMID 24618737, 2014). "Based on these discoveries, clinical trials are underway testing combined inhibition of BRAF and EGFR in colorectal cancer (NCT01750918)." (PMID 25520658, 2014). "Anti-EGFR therapy is commonly used to treat colorectal cancer (CRC), although only a subset of patients benefit from the treatment." (PMID 24940619, 2014). "Oncogenic activation of signaling pathways downstream of the EGFR, as induced by mutated KRAS or BRAF, is important for the progression of colorectal cancer." (PMID 25267307, 2014). "In colorectal cancer, different mutations in KRAS (exon 12 and 13), associated with resistance to EGFR monoclonal antibody therapy, were found in the same patient." (PMID 25222836, 2014). "Targeting epidermal growth factor receptor (EGFR) has been one of the most effective colorectal cancer strategies." (PMID 25032217, 2014). "In order to inhibit the activity of the epidermal growth factor receptor (EGFR), anti-EGFR has been included in the therapeutic arsenal for patients with tumours of epithelial origin (lung and colorectal cancer)." (PMID 24649376, 2014).
colorectal cancer (continued). "Although EGFR-targeted therapy has been beneficial to colorectal cancer patients, several studies have showed this clinical benefit was restricted to patients with wild-type KRAS exon 2 colorectal cancer." (PMID 25427200, 2014). "In a recent research, it is find that ARNO is highly expressed in colorectal cancer, and the expression is correlated with the EGFR and IGF-IR pathways." (PMID 24618737, 2014). "We then detected the downstream of EGFR and IGF-IR in association with colorectal cancer incidence rates." (PMID 24618737, 2014). "Colorectal carcinomas that are wild type for KRAS are often sensitive to EGFR blockade and therefore KRAS testing can prevent both ineffective treatment and treatment-associated toxicity." (PMID 24676216, 2014). "For example, colorectal carcinomas that are wild type for KRAS are frequently treated with monoclonal antibodies targeting the Epidermal Growth Factor Receptor (EGFR)." (PMID 24676216, 2014). "Here we show that concomitant immunoexpression of EGFR and TATI is an independent prognostic factor for favorable survival in colorectal cancer, and it is a stronger prognostic factor than EGFR or TATI/SPINK1 alone." (PMID 24204699, 2013). "A further distinguishing feature regarding the testing of EGFR in colorectal cancer and NSCLC is that in the latter, IHC positivity or high EGFR gene copy numbers showed no conclusive correlation with treatment response." (PMID 24199171, 2013). "For example, benefits of cetuximab and panitumumab in colorectal cancer and benefits of the EGFR tyrosine kinase inhibitors (TKIs) erlotinib and gefitinib in NSCLC are respectively associated with presence vs absence of KRAS and EGFR mutations." (PMID 23587187, 2013). "In conclusion, ARNO, an important isoform of the cytohesin family, is highly expressed in colorectal cancer cells and enhances EGFR signaling, which contributes to tumor differentiation, survival and proliferation." (PMID 23420529, 2013). "In conclusion, our meta-analysis provides evidence that EGFR gene copy number is a prognostic marker for survival among patients receiving anti-EGFR mAbs for advanced colorectal cancer." (PMID 23441167, 2013). "More than half of patients with KRAS-wild type advanced colorectal cancer (CRC) fail anti-EGFR monoclonal antibodies." (PMID 23374602, 2013). "With more than 940,000 new colorectal cancer cases worldwide each year, the use of anti-EGFR targeted therapies are faced with main issues, an economical one: who pays for the test or the drugs and a medical one: who performs the test?" (PMID 23935912, 2013). "Monoclonal antibodies directed against EGFR, including cetuximab and panitumumab, have shown efficacy both as monotherapies and in combination with chemotherapy for the treatment of colorectal cancer (CRC)." (PMID 24152305, 2013). "Here, we systematically investigated the impact of ECM on phenotype, gene expression, EGFR signaling pathway, and on EGFR inhibition in commonly used colorectal cancer (CRC) cell lines." (PMID 23555746, 2013). "In colorectal cancer cells, sensitivity to an anti-EGFR drug (i.e., gefitinib) can be improved by the pharmacological inhibition of insulin receptor isoform-A." (PMID 23702846, 2013). "Currently therapeutic treatments toward advanced colorectal cancers are mainly focused on the design of therapeutic agents that is targeted to the epidermal growth factor receptor (EGFR), the monoclonal blocking antibodies such as cetuximab and panitumumab." (PMID 23451083, 2013). "The epidermal growth factor receptor (EGFR), a target for treatment of advanced colorectal cancer, belongs to a transmembrane glycoprotein of the ErbB tyrosine kinase receptor family." (PMID 24204699, 2013). "In concordance with previous findings, we observed EGFR overexpression in colorectal cancer samples." (PMID 24204699, 2013).
colorectal cancer (continued). "For the past decade, targeting EGFR activity using gefitinib and erlotinib has been used successfully to treat certain lung and colorectal cancer patients." (PMID 24131756, 2013). "Recently, certain individuals with wild-type Kras gene colorectal cancer have benefited from therapies targeting the EGFR." (PMID 23420529, 2013). "Two signaling pathways downstream of the epidermal growth factor receptor (EGFR) are dysregulated in the majority of colorectal cancers (CRC): the mitogen-activated protein kinase (MAPK) and the phosphoinositide-3-kinase (PI3K) pathway." (PMID 24156022, 2013). "Therapeutic antibodies targeting EGFR have activity in advanced colorectal cancer, but results from clinical trials are inconsistent and the population in which most benefit is derived is uncertain." (PMID 23725851, 2013). "Patient clinicopathological characteristics and their correlation with EGFR immunoreactivity in 520 colorectal cancer patients assessed with chi-square test (a Mann-Whitney test)." (PMID 24204699, 2013). "In 2003, therapeutic antibodies targeting EGFR entered phase 3 trials in advanced colorectal cancer." (PMID 23725851, 2013). "Given the upregulation of EGFR expression and activity in colorectal cancer, small molecule inhibitors of EGFR have also been developed and tested for colorectal cancer therapy." (PMID 24276379, 2013). "Another promising biomarker of anti-EGFR resistance is represented by BRAFV600E mutation, that occurs in about 10% of colorectal cancers." (PMID 23536897, 2013). "Our present results are compatible with the theory that COX-2 and EGFR signalling pathways are inversely related in colorectal cancer tissue." (PMID 24171795, 2013). "For colorectal cancer (CRC) the major advances have involved drugs that target the epidermal growth factor receptor (EGFR) and vascular endothelial growth factor (VEGF)." (PMID 23930204, 2013). "Overexpression and aberrant function of EGFR have been identified in a variety of human tumors, including colorectal cancer." (PMID 23251236, 2013). "Here we show that EGFR immunoexpression is an independent marker for favourable prognosis in colorectal cancer patients." (PMID 24204699, 2013). "Current treatment target toward advanced colorectal cancers is mainly focused on the epidermal growth factor receptor (EGFR) signaling, but its additive effects with chemotherapy are still limited." (PMID 23451083, 2013). "Methods used to evaluate the quantity of EGFR in colorectal cancers include immunohistochemistry, ligand binding, immunoblotting, fluorescence in situ hybridization analysis and a variety of molecular techniques." (PMID 23824671, 2013). "Nowadays, colorectal cancer expressing epidermal growth factor receptor (EGFR), a client protein of HSP90, has been targeted using tyrosine kinase inhibitors and monoclonal antibodies." (PMID 23840275, 2013). "Here, we investigated the capacity of the anti-EGFR mAb C225 to modulate the radiosensitivity and inhibit cellular proliferation in human colorectal cancer cells." (PMID 24053278, 2013). "Myofibroblasts, TNF-α, LPA, EGFR, and COX-2 have all been strongly and independently implicated in the development of colorectal cancer." (PMID 23688423, 2013). "The epidermal growth factor receptor (EGFR) gene copy number (GCN) has been previously demonstrated to correlate with the clinical outcome of colorectal cancer (CRC) treated with anti-EGFR monoclonal antibodies (mAbs), although it remains controversial." (PMID 23441167, 2013). "EGFR-targeted treatments have been used for metastasized colorectal cancers, but the value of EGFR immunoexpression to predict the efficiency of adjuvant treatment is controversial." (PMID 24204699, 2013). "Cyclooxygenase (COX) and epidermal growth factor receptor (EGFR) activities promote progression of colorectal cancer." (PMID 24171795, 2013).
colorectal cancer (continued). "In fact, application of the anti-EGFR antibody cetuximab turned out beneficial in treatment of patients suffering from colorectal cancers and HNSCC." (PMID 23724085, 2013). "We searched Medline using OvidSP for published randomised clinical trials in advanced colorectal cancer involving an anti-EGFR monoclonal antibody." (PMID 23725851, 2013). "The feasibility and efficacy of the inhibitory effects of LRIG1 on tumor through inhibiting EGFR signaling activity have been studied in renal cancer, glioma, squamous cell carcinoma of skin, colorectal cancer and prostate cancer." (PMID 24314030, 2013). "Kaulfuβ and colleagues reported that dual silencing of insulin-like growth factor receptor and epidermal growth factor receptor resulted in an increased apoptosis rate and inhibition of cell proliferation in colorectal cancer cells." (PMID 23853530, 2013). "Here we show that in roughly two out of three colorectal carcinoma samples EGFR and TATI/SPINK1 are co-expressed." (PMID 24204699, 2013). "The family of epidermal growth factor receptor (EGFR) and c-Met are RTKs that have been frequently reported in colorectal carcinoma progression and metastasis." (PMID 24205104, 2013). "A phase II trial, however, has concluded that the IGF-1R neutralizing antibody IMC-A12, alone or in combination with the EGFR antibody cetuximab, is insufficient for the treatment of colorectal carcinomas." (PMID 24182354, 2013). "Currently, KRAS is the only potential biomarker for predicting the efficacy of anti-EGFR monoclonal antibodies (mAb) in colorectal cancer (CRC)." (PMID 22043994, 2012). "The introduction of K-RAS testing for colorectal cancer patients offered the long-awaited clinical opportunity to exclude resistant tumours from the treatment with anti-EGFR antibodies." (PMID 22490361, 2012). "Some medical centers thus began offering cetuximab off-label to colorectal cancer patients with non EGFR-expressing tumors." (PMID 22999017, 2012). "We have previously reported that the blockade of EGF stimulation significantly suppressed colorectal cancer cell growth, suggesting that the EGFR pathway plays an important role in proliferation of these cells." (PMID 22788833, 2012). "K-RAS mutation testing is a validated biomarker in clinical practice to predict anti-EGFR treatment outcome in colorectal cancer." (PMID 27398239, 2012). "Molecular knowledge led investigators to pursue all prelicensure trials in colorectal cancer patients with EGFR-expressing tumors." (PMID 22999017, 2012). "More recently, Panitumumab, a humanized anti-EGFR mAb, was also approved to colorectal cancer treatment, with good results in therapeutic efficacy." (PMID 23207070, 2012). "The efficacy of combined therapies of oxaliplatin-based chemotherapy and anti-epidermal growth factor receptor (anti-EGFR) monoclonal antibodies (MAbs) remains controversial in colorectal cancer (CRC)." (PMID 23226426, 2012). "As summarized in this paper, clinical and translational investigators have been productive in trying to identify either optimal strategies or expanded roles for EGFR-targeted therapy as treatment for colorectal cancer." (PMID 23091721, 2012). "Amphiregulin (AREG) and Epiregulin (EREG), ligands of EGFR, are reported to be predictive biomarkers of colorectal cancer patients treated with Cetuximab, an anti-EGFR antibody." (PMID 22409860, 2012). "Another potential strategy to improve survival from colorectal cancer is to further capitalize on the pathways that have had some therapeutic potential in this disease, EGFR and VEGFR." (PMID 22701615, 2012). "Currently, mutational profiles are applied for selection of targeted therapeutics for e.g. BRAF inhibitors in malignant melanoma and BRAF and EGFR targeting in lung- and colorectal cancers." (PMID 23300780, 2012).
colorectal cancer (continued). "Activation of the MAPK pathway is initiated by ligand binding to a receptor tyrosine kinase, such as, epidermal growth factor receptor (EGFR) that has been shown to be critical in the development of colorectal cancer." (PMID 22792460, 2012). "Due to the known expression of EGFR in colorectal cancer, a phase II trial of cetuximab, an anti-EGFR monoclonal antibody, in patients with refractory EGFR-positive (assessed by immunohistochemistry) colorectal cancer was undertaken." (PMID 21403829, 2011). "Some studies report that EGFR gene amplification (assessed by in situ hybridization methods) is uncommon in colorectal cancer." (PMID 21403829, 2011). "Growing knowledge suggests, however, that EGFR-mediated tumourigenic mechanisms as well as EGFR-targeted therapeutic approaches are very different for this tumour type when compared with better understood NSCLC or colorectal cancers." (PMID 21792199, 2011). "Clinical studies have shown that the combination of irinotecan and the EGFR inhibitor cetuximab is preferable for patients with irinotecan-refractory colorectal cancer." (PMID 21997136, 2011). "The influence of ligand expression on response to EGFR-targeted agents has already been described in colorectal cancer." (PMID 21792199, 2011). "Activating mutation of KRAS and BRAF are focused on as potential prognostic and predictive biomarkers in patients with colorectal cancer (CRC) treated with anti-EGFR therapies." (PMID 21285991, 2011). "Cox-2 was coexpressed with EGFR in human colorectal cancer and bronchial adenocarcinomas and induced in a human glioma cell line." (PMID 21813027, 2011). "Until a standard method of EGFR staining and reporting is adopted, the significance of EGFR protein expression in colorectal cancer remains controversial." (PMID 21403829, 2011). "The epidermal growth factor receptor (EGFR) pathway is a therapeutic target in the management of colorectal cancer (CRC)." (PMID 21437184, 2011). "The epidermal growth factor receptor (EGFR) and its downstream signaling pathways are involved in the development and progression of several human tumors, including colorectal cancer." (PMID 21403829, 2011). "In practice, it is considered that EGFR-positive as well as KRAS wild-type colorectal cancer patients have satisfied criteria for cetuximab therapy." (PMID 21554739, 2011). "EGFR-targeted monoclonal antibodies (cetuximab and panitumumab) have also been recently licensed in the first-line advanced colorectal cancer setting and cetuximab has been explored in an intermittent strategy in the Nordic VII22 and COIN-B trials." (PMID 21641867, 2011). "Another neo-adjuvant drug for colorectal cancer is Cetuximab, also known as Erbitux, a monoclonal antibody that inhibits the epidermal growth factor receptor (EGFR), involved in cell differentiation and proliferation." (PMID 24212791, 2011). "Globally, 30 patients (58%) showed EGFR promoter hypermethylation either in primary colorectal cancer or in metastasis." (PMID 21559018, 2011). "Although EGFR has been reported to be overexpressed in anywhere from 25% to 82% of colorectal cancers, some recent studies report protein overexpression (defined as 2+ and/or 3+ staining or in >50% of cells) in 35 to 49% of cases." (PMID 21403829, 2011). "The lack of sensitivity of IHC to identify low expression levels of EGFR was comprehensively illustrated in colorectal cancer." (PMID 22613809, 2011). "Epidermal growth factor receptor inhibitors achieved a better clinical response rate for colorectal carcinomas when used in combination with cytostatic drugs, including irinotecan, 5-FU, and OXA." (PMID 21997136, 2011). "Prognostic and predictive significance of epidermal growth factor receptor (EGFR) in colorectal carcinomas (CRCs) is still controversial." (PMID 22050898, 2011).